L1CAM (L1 cell adhesion molecule)
Diseases named in the same sentence as L1CAM in open-access papers (continued):
Sharing a sentence is not in itself a finding about the gene and the disease.
synucleinopathy (3 papers, 2024 to 2025). A neurodegenerative disease that is characterized by the abnormal accumulation of aggregates of alpha-synuclein protein in neurons, nerve fibers or glial cells. "Another possible marker of α-synucleinopathies is the L1 cell adhesion molecule (L1CAM)-enriched extracellular vesicles (L1EVs)." (PMID 40136601, 2025). "Indeed, extracellular exosomes (i.e., L1CAM positive) were consistently enriched pathways in agreement with our previous BAR studies, suggesting that αsyn aggregates in synucleinopathy brain partly resemble exosomes and supporting the hypothesis that αsyn/αsyn aggregates can spread via exosomes." (PMID 40122840, 2025).
vulvar cancer (3 papers, 2016 to 2017). "When combining the two cohorts, the statistical power of our analyses increases, which underlines the potential prognostic value of L1CAM expression in vulvar cancer." (PMID 27028855, 2016). "Therefore L1CAM proves to have potential as a reliable biomarker that can be used to discriminate high risk from low risk vulvar cancer patients." (PMID 27028855, 2016). "L1CAM expression has shown to be a marker for poor disease outcome in several types of cancer and this is study is the first to evaluate the prognostic capacity in vulvar cancer." (PMID 27028855, 2016). "Finally, in a pilot in vitro study we have examined the role of L1CAM in invasion of vulvar cancer cells." (PMID 27028855, 2016). "Furthermore our pilot in vitro data show an important role specifically for L1CAM in the invasive properties of spindle shaped vulvar cancer cells." (PMID 27028855, 2016). "In addition, the potential to use L1CAM as a target for therapy based on our vulvar cancer cell invasion assays, warrants further investigation." (PMID 27028855, 2016). "We can conclude that L1CAM expression represents a promising prognostic biomarker in vulvar cancer." (PMID 27028855, 2016). "Therefore, we do not expect that Wnt-signalling through β-catenin is a major factor in the upregulation of L1CAM in vulvar cancer." (PMID 27028855, 2016). "Together, our findings indicate that L1CAM upregulation may be a consequence of EMT-like changes in vulvar cancer." (PMID 27028855, 2016). "L1CAM expression has not been examined in vulvar cancer before, but some studies have reported a relation between morphological features of EMT and a worse survival in vulvar cancer." (PMID 27028855, 2016).
arthrogryposis (2 papers, 2024 to 2026). A rare, non-progressive congenital disorder characterized by multiple joint contractures which are present at birth. "Mutations in MAGEL2 and L1CAM have been associated with congenital hypopituitarism and arthrogryposis in a small series, highlighting the need for further study." (PMID 41499205, 2026).
autism (2 papers, 2021 to 2025). Persistent deficits in social interaction and communication and interaction as well as a markedly restricted repertoire of activity and interest as well as repetitive patterns of behavior. "Additionally, the interaction between L1CAM and ankyrins guides neuronal adhesion and signaling, where abnormalities are associated with neurodevelopmental disorders like autism." (PMID 39954672, 2025).
carcinosarcoma (2 papers, 2025). A malignant tumor composed of a mixture of carcinomatous and sarcomatous elements. "Certain factors such as tumor size and specific histopathological and molecular features like TP53abn and L1CAM positivity, along with tumor subtypes such as clear cell, serous, undifferentiated, mixed (>10 %), and carcinosarcomas, are linked to a poorer prognosis and an increased risk of relapse." (PMID 39923442, 2025).
clear cell carcinomas (2 papers, 2021 to 2025). "In serous and clear cell carcinomas, the authors described L1CAM expression and ER/PR/E-cadherin negativity (percentages not given)." (PMID 40870967, 2025).
colon adenocarcinoma (2 papers, 2018 to 2020). "Furthermore, blocking L1CAM decreases adherence and migration of tumor cells from colon adenocarcinoma to the nervous system showing involvement of L1CAM in perineural invasion in CRC." (PMID 33167483, 2020).
colorectal adenocarcinoma (2 papers, 2016 to 2025). The most common type of colorectal carcinoma. "High L1CAM expression was associated with invasive tumor growth (pTa vs. pT2-4) in urothelial carcinoma of the bladder (p<0.0001) and with mismatch repair deficiency in colorectal adenocarcinoma (p=0.0064)." (PMID 41328908, 2025). "High L1CAM expression was associated with invasive tumor growth (pTa vs. pT2–4) in urothelial carcinoma of the bladder (p < 0.0001) and with mismatch repair protein deficiency (p = 0.0064) and left-sided tumor location (p = 0.0104) in colorectal adenocarcinoma." (PMID 41328908, 2025).
endometrioid tumor (2 papers, 2023 to 2025). A benign, borderline, or malignant epithelial tumor of the female reproductive system characterized by the presence of glands and/or cysts lined by neoplastic cells that resemble endometrial cells. "In lower-risk histologies, specifically endometrioid tumors, L1CAM has impactful prognostic value." (PMID 37200263, 2023). "Notably, the prognostic relevance of L1CAM restricted to endometrioid EC, but not observed in non-endometrioid tumors, had already been reported in a collaborative ENITEC study evaluating its tissue expression in a series of 1199 EC cases." (PMID 41301764, 2025).
esophageal cancer (2 papers, 2021 to 2022). A primary or metastatic malignant neoplasm involving the esophagus. "To explore the biological function of L1CAM in esophageal carcinoma, we used qRT-PCR to assess the L1CAM expression in 4 ESCC cell lines (EC1, KYSE70, TE1, and KYSE450) and an immortalized esophageal epithelial cell line, Het-1α." (PMID 33710805, 2021).
lymphoma (2 papers, 2011 to 2020). A malignant (clonal) proliferation of B- lymphocytes or T- lymphocytes which involves the lymph nodes, bone marrow and/or extranodal sites. "Earlier studies in a mouse lymphoma model also demonstrated that mice bearing L1CAM positive tumours survived longer than mice bearing L1CAM negative tumours." (PMID 32291413, 2020).
major depressive disorder (2 papers, 2021 to 2023). An episode of depression lasting two or more weeks without an intervening episode of mania. "Compared to healthy controls, the number of L1CAM rich exosomes was increased in patients with major depressive disorder (MDD), and these patients had increased concentrations of insulin receptor substrate −1 (IRS-1) in L1CAM+ exosomes, which is associated with suicidality and anhedonia." (PMID 34588957, 2021). "In addition, miR-486-5p from L1CAM-enriched plasma EVs was recently reported to be associated with antidepressant treatment response in Major Depressive Disorder (MDD), although L1CAM as a neuronal EV marker may not be ideal, at least in proteomics studies." (PMID 38019909, 2023).
mastocytosis (2 papers, 2019 to 2022). A clonal myeloproliferative neoplasm characterized by the proliferation and accumulation of neoplastic mast cells in one or multiple organs or organ systems. "The study revealed that two proteins, neural cell adhesion molecule L1 (L1CAM/CD171) and dipeptidyl peptidase 4 (DDP4/CD26), served as the novel biomarkers for human skin mast cells in normal, psoriatic, and mastocytosis skin." (PMID 30845706, 2019).
metastatic melanoma (2 papers, 2013 to 2018). A melanoma that has spread from its primary site to another anatomic site. "Complex-type oligosaccharides in L1CAM enhance the invasiveness of metastatic melanoma cells." (PMID 22544341, 2013).
microcephaly (2 papers, 2015 to 2023). A congenital or acquired developmental disorder in which the circumference of the head is smaller than normal for the person's age and sex. "Other genes within the combined network are involved in neuronal progenitor cell proliferation, a common mechanism underlying microcephaly (RAC1 and GNB1) and neuronal development (CEBPB, L1CAM, MAPT, PAK2, SPTBN1, and YWHAE)." (PMID 25781962, 2015).
osteosarcoma (2 papers, 2020 to 2025). A usually aggressive malignant bone-forming mesenchymal neoplasm, predominantly affecting adolescents and young adults. "Although B7H3, L1CAM, CSPG4, and Lewis Y were also overexpressed by some osteosarcoma cell lines, the ADTC potency of their respective BsAb was much weaker than GD2-BsAb or HER2-BsAb." (PMID 33303017, 2020).
Renal neoplasm (2 papers, 2024 to 2025). The presence of a neoplasm of the kidney. "Interestingly, another recently identified indolent renal neoplasm, papillary renal neoplasm of reverse polarity, has been consistently found to exhibit diffuse membranous staining for both L1CAM and GATA3." (PMID 40805143, 2025).
renal oncocytoma (2 papers, 2024 to 2025). "Additionally, L1CAM IHC proved useful in distinguishing LOT from renal oncocytoma and EVT." (PMID 40805143, 2025).
stenosis (2 papers, 2020 to 2025). "Unlike patients hemizygous for L1CAM pathogenic variants, who have additional radiological findings such as aqueductal stenosis and agenesis of the corpus callosum with resultant psychomotor morbidity, the 4 patients hemizygous for the AMOT variant developed normally after early VP shunt insertion." (PMID 40892511, 2025).
acrocallosal syndrome (1 paper, 2010). Acrocallosal syndrome (ACS) is a polymalformative syndrome characterized by agenesis of corpus callosum (CC), distal anomalies of limbs, minor craniofacial anomalies and intellectual deficit. "In addition, two cases with both acrocallosal syndrome and HSCR have been also linked to L1CAM mutations." (PMID 20860806, 2010).
adolescent idiopathic scoliosis (1 paper, 2014). A scoliosis with no known cause arising in adolescent. "A previous genome-wide association study (GWAS) suggested a strong association between the single nucleotide polymorphism (SNP) rs10510181 in the proximity of the gene encoding a cell adhesion molecule with homology to L1CAM (CHL1) and adolescent idiopathic scoliosis (AIS) in Caucasians." (PMID 24512353, 2014).
alcohol (1 paper, 2011). "Alcohol’s ability to specifically inhibit the adhesive properties and axon and dendrite outgrowth mediated by the L1 cell adhesion molecule (CAM) has implicated L1CAM as a target for developmental alcohol neurotoxicity." (PMID 23580044, 2011).
atherosclerosis (1 paper, 2025). A disease characterized by the build-up of fatty material and calcium deposition in the arterial wall resulting in partial or complete occlusion of the arterial lumen. "Canonical pathways identified to be altered in TI heifers at birth and 4 months of age include epithelial adherens junction signaling (activated), atherosclerosis signaling (activated), Signaling by Rho family GTPases (activated), cardiac conduction (inhibited), and L1CAM interactions (inhibited)." (PMID 40316897, 2025).
biliary tract cancer (1 paper, 2017). "Recently, we found that L1CAM is aberrantly expressed in biliary tract cancers such as ICC, ECC, and gall bladder carcinoma (GBC), and its high expression correlates with poor prognosis and metastasis." (PMID 28166242, 2017).
cancer testis (1 paper, 2013). "We also studied the relationship to cancer testis (CT-X) antigens that co-localize with L1CAM on chromosome Xq28, a region that is often activated in human tumors." (PMID 23530769, 2013).
carcinoma in situ (1 paper, 2014). "Staining of the L1CAM was occasionally detected in 8% (6 of 72 cores) of tumor tissues, which were classified as carcinoma in situ with no regional lymph node or distant metastasis (T2N0M0 and T3N0M0), with major localization at the interphase between the tumor and stroma." (PMID 25294816, 2014).
cardiomyopathy (1 paper, 2021). A disease of the heart muscle or myocardium proper. "To evaluate the clinical relevance of our findings, we analysed vascular L1CAM expression in cardiac tissues from patients with cardiomyopathy (n = 12) compared with that in normal cardiac tissues (n = 8)." (PMID 34078883, 2021). "Our data revealed that cardiovascular ECs with persistent DNA damage showed upregulated L1CAM expression with increased EndMT occurrence, which can be attributed to the development of cardiomyopathy." (PMID 34078883, 2021). "We show that cardiomyopathy patient-derived cardiovascular ECs with persistent DNA damage show upregulated L1CAM and EndMT, indicating clinical applicability of Ab417." (PMID 34078883, 2021).
clear cell ovarian carcinomas (1 paper, 2020). "The authors showed that L1CAM levels correlated with poor disease-specific overall survival and disease-free survival in endometrioid, but not in clear cell ovarian carcinomas." (PMID 32429448, 2020).
colitis (1 paper, 2023). Inflammation of the colon. "As a result, the heightened tuft-cell-initiated communication through L1CAM–integrin interactions leads to the activation of ILC2, which is critical in the downstream immune responses that induce and maintain inflammation and increase the potential risk of colitis, even cancer development." (PMID 37893107, 2023).
cutaneous melanoma (1 paper, 2023). A primary melanoma arising from atypical melanocytes in the skin. "The major findings in this report are that (i) loss of α-syn expression in two human cutaneous melanoma cell lines significantly decreases L1CAM, N-cadherin, and cell motility)." (PMID 37286800, 2023). "In sum, we have shown that loss of α-syn expression in two human cutaneous melanoma cell lines results in significant decreases in two adhesion proteins, L1CAM and N-cadherin, and concomitant significant decreases in motility." (PMID 37286800, 2023).
desmoid tumor (1 paper, 2017). A desmoid tumor (DT) is a benign, locally invasive soft tissue tumor associated with a high recurrence rate but with no metastatic potential. "Therefore, over-expression of miR-21-3p and down-expression of miR-197-3p targeting L1CAM, SERPINA3 and TSPAN3, respectively, could induce or maintain the inflammatory process in mutated desmoid tumor." (PMID 28418912, 2017).
diabetic retinopathy (1 paper, 2017). "In diabetic retinopathy 34 genes including AP15, GRB2, IL17A, PLXDC1, C5 and L1CAM were studied in a single year in which, C5 and L1CAM are reported as recently as in 2016." (PMID 28761062, 2017).
Encephalopathy (1 paper, 2010). Encephalopathy is a term that means brain disease, damage, or malfunction.
endometrioid ovarian carcinomas (1 paper, 2016). "Correspondingly, high L1CAM transcript levels were most frequently found in serous followed by endometrioid ovarian carcinomas and the lowest L1CAM mRNA was detected in mucinous subtype." (PMID 27174921, 2016).
Ewing sarcoma (1 paper, 2020). A small round cell tumor that lacks morphologic, immunohistochemical, and electron microscopic evidence of neuroectodermal differentiation. "Similar to PHF2, higher L1CAM expression is significantly associated with inferior clinical outcome in Ewing sarcoma." (PMID 33196691, 2020). "These genes include L1CAM, which is associated with adverse outcomes in Ewing sarcoma, and promotes migratory and invasive properties." (PMID 33196691, 2020). "We further show that L1CAM promotes Ewing sarcoma cell migratory and invasive properties when expressed at high levels." (PMID 33196691, 2020). "Here, we identify L1CAM as variably expressed in Ewing sarcoma, strongly induced upon EWS/Fli1 downregulation, and strongly associated in expression with adverse clinical outcome." (PMID 33196691, 2020). "Our expression survey revealed a broad range of L1CAM expression levels in patient-derived Ewing sarcoma cell lines, ranging from low levels in TC32 cells to high levels in A4573, SK-ES-1 and SK-N-MC cells." (PMID 33196691, 2020). "Thus, L1CAM is an adverse prognostic factor in Ewing sarcoma, and promotes migratory and invasive properties." (PMID 33196691, 2020). "It will also be of interest to more fully understand mechanisms controlling its highly variable expression in Ewing sarcoma, which could present alternative opportunities to inhibition of L1CAM effects." (PMID 33196691, 2020). "Our studies provide evidence that, in Ewing sarcoma, KDM5A activates expression of L1CAM (and MCAM) via a demethylase-independent mechanism." (PMID 33196691, 2020).
eye cancer (1 paper, 2022). "In order to further establish L1CAM as a possible therapeutic target in RB treatment, especially in the context of chemotherapeutic resistances, we investigated L1CAM's function in the development and progression of this eye cancer." (PMID 34228897, 2022).
gastric tumor (1 paper, 2013). "In 42 gastric tumor tissue samples and matched normal gastric mucosa, average expressions of L1CAM were 0.0403 ± 0.0069 and 0.0093 ± 0.0010, respectively, and were significant different (t = 2.845, P = 0.006)." (PMID 24422715, 2013). "L1CAM was over-expressed in 25 gastric tumor tissue samples compared with matched normal gastric mucosa." (PMID 24422715, 2013).
Hepatic fibrosis (1 paper, 2015). The presence of excessive fibrous connective tissue in the liver. "The most highly represented gene families in the grouping of hepatic fibrosis were the collagens (Col, n = 10) while in the category of axonal guidance were members of different gene families including NGF, PlexinB1, EphrinB3, Semaphorin6C, and L1CAM." (PMID 26156969, 2015).
heterotopia (1 paper, 2013). "Some of these changes, such as the upregulation of L1cam (which encodes an immunoglobulin superfamily cell adhesion molecule), might hypothetically interfere with cell migration and cause heterotopia." (PMID 24252393, 2013).
histiocytic neoplasm (1 paper, 2025). Histiocytic tumors are a heterogeneous group of tumors and tumorlike masses commonly associated with histologically identical extracranial lesions. "In addition, we have investigated L1CAM expression in a small series of mesenchymal and histiocytic neoplasms/proliferations, which were all negative, suggesting that L1CAM expression may be used as a supportive marker for the diagnosis of FDCS." (PMID 40289262, 2025).
Hyperammonemia (1 paper, 2022). An increased concentration of ammonia in the blood. "The increase in L1CAM content in EVs from the plasma of MHE patients would indicate an increase in neuron derived EV secretion, which could be due to a tonic activation of NMDA receptors induced by hyperammonemia." (PMID 36293192, 2022).
hypothyroidism (1 paper, 2024). Abnormally low levels of thyroid hormone. "However, since multiple underlying mechanisms are associated with hypothyroidism, other possible targets associated with ART that could ameliorate hypothyroidism and its complications were investigated such as the L1 cell adhesion molecule." (PMID 39155377, 2024).
invasive breast carcinoma (1 paper, 2017). A carcinoma that infiltrates the breast parenchyma. "Finally, the expression of L1CAM, Mint3 and MT1-MMP in human invasive breast cancer specimens was analysed by immunohistochemistry." (PMID 28504692, 2017).